DDX17 (DEAD-box helicase 17)
Diseases named in the same sentence as DDX17 in open-access papers (continued):
Sharing a sentence is not in itself a finding about the gene and the disease.
heart failure (2 papers, 2024 to 2025). Inability of the heart to pump blood at an adequate rate to meet tissue metabolic requirements. "Under the pathological conditions caused by various stimuli, cardiomyocyte-specific Ddx17 knockout can aggravate the loss of cardiac function, myocardial fibrosis and myocardial remodeling, resulting in heart failure." (PMID 38782919, 2024). "Western blot showed that TAC-induced heart failure caused cardiomyocyte apoptosis and significantly reduced Ddx17 mRNA and protein expression in the myocardium." (PMID 38782919, 2024). "Taken together, our results suggest that loss of DDX17 can lead to the deregulation of mitochondrial homeostasis and loss of cardiomyocyte function, whereas replenishment of DDX17 protects cardiomyocytes and inhibits the development of heart failure." (PMID 38782919, 2024). "Therefore, the decreased expression of DDX17 may be closely correlated with heart failure caused by various pathological stimuli in vivo." (PMID 38782919, 2024). "In cardiovascular system, DDX17 is closely related to the development of heart failure, repair of cardiac damage and myocardial differentiation." (PMID 41322492, 2025). "Testing of left ventricular myocardial biopsy samples from clinical heart failure patients also suggests a significant positive correlation between patients' left ventricular ejection fraction (EF%) and DDX17 expression in myocardial tissue." (PMID 41322492, 2025). "The mRNA/protein levels of DDX17 in tissue samples are significantly correlated with the EF value of heart failure, the metastasis status of cancer, and the expression of cfRNA/exosomes in blood can be used as convenient detection indicators." (PMID 41322492, 2025). "Our study found that DDX17 expression was positively correlated with left ventricular EF in myocardial biopsy samples from heart failure patients and in Dox-induced acute heart failure and TAC-induced chronic heart failure mouse models." (PMID 38782919, 2024). "To investigate the expression of DDX17 in the mouse heart failure model, we established a chronic heart failure mouse model with transverse aortic constriction (TAC) and an acute heart failure mouse model with doxorubicin (Dox)." (PMID 38782919, 2024). "We also demonstrated that the mRNA level of DDX17 was negatively correlated with that of DRP1 in human heart failure samples (r = −0.5950, P = 0.0193)." (PMID 38782919, 2024). "Cardiomyocyte-specific knockout of Ddx17 promotes autophagic flux blockage and cardiomyocyte apoptosis, leading to progressive cardiac dysfunction, maladaptive remodeling and progression to heart failure." (PMID 38782919, 2024). "We generated cardiomyocyte-specific Ddx17-knockout mice (Ddx17-cKO), cardiomyocyte-specific Ddx17 transgenic mice (Ddx17-Tg), and various models of cardiomyocyte injury and heart failure (HF)." (PMID 38782919, 2024). "DDX17 expression is downregulated in the mouse myocardium of heart failure and myocardial injury." (PMID 41322492, 2025). "Abnormal DDX17 expression may be one of the common pathways of myocardial injury and heart failure, and DDX17 may also be potentially valuable for the diagnosis and treatment of heart failure induced by a variety of pathological factors in clinical practice." (PMID 38782919, 2024). "From the results of in vivo and in vitro experiments, it was found that aberrant reduction of DDX17 expression may be one of the common pathways in the development of cardiomyocyte injury and heart failure by many pathological factors." (PMID 38782919, 2024). "DDX17 is downregulated in the myocardium of mouse models of heart failure and cardiomyocyte injury." (PMID 38782919, 2024). "Therefore, the aim of this study was to investigate the role of DDX17 in the maintenance of normal cardiac function and in the pathological conditions of cardiomyocyte injury and heart failure." (PMID 38782919, 2024).
heart failure (continued). "Cardiomyocyte-specific knockdown of DDX17 promotes autophagic flux blockade and cardiomyocyte apoptosis, leading to progressive cardiac dysfunction, maladaptive remodeling, and progression to heart failure, whereas restoration of DDX17 expression protects the heart against pathological stresses." (PMID 41322492, 2025). "Therefore, the expression of DDX17 in myocardial biopsy samples may have important clinical application value in diagnosing and evaluating the stage of heart failure." (PMID 38782919, 2024). "Thus, DDX17 plays a very important role in maintaining normal cardiac structure and function, and its cardiomyocyte-specific knockout can lead to abnormalities in cardiac structure and function and aggravate Dox-induced heart failure." (PMID 38782919, 2024). "Therefore, in the following experiments, we used a stable in vivo model of acute heart failure established by intraperitoneal injection of Dox into mice and cellular injury models such as doxorubicin, hypoxia, and H2O2 to explore the role and mechanism of DDX17 in the development of heart failure." (PMID 38782919, 2024). "We also investigated the correlation of DDX17 expression with cardiac function and DRP1 expression in myocardial biopsy samples from patients with heart failure." (PMID 38782919, 2024). "Therefore, regulating the expression of DDX17 in cardiomyocytes, maintaining mitochondrial homeostasis and normal autophagy function, and reducing cardiomyocyte apoptosis under pathological conditions are potential clinical diagnosis and treatment targets for myocardial injury and heart failure." (PMID 38782919, 2024). "When DDX17 expression is reduced, transcriptional repression of BCL6 is attenuated, leading to increased DRP1 expression and mitochondrial fission, which in turn leads to impaired mitochondrial homeostasis and heart failure." (PMID 38782919, 2024). "Thus, under pathological conditions, aberrantly downregulated DDX17 expression can lead to reduced BCL6 transcriptional repression, resulting in cardiomyocyte injury and the development of heart failure." (PMID 38782919, 2024). "Our study found that DDX17 is involved in the regulation of mitochondrial homeostasis in cardiomyocytes mainly through the regulation of DRP1 expression and mitochondrial fission, which are involved in the maintenance of normal cardiac function and inhibition of heart failure." (PMID 38782919, 2024). "Consistent with these structural changes, the left ventricular EF of patients with heart failure showed a significant positive correlation with the mRNA level of DDX17 (r = 0.5644, P = 0.0284) and a negative correlation with the mRNA level of DRP1 (r = −0.6526, P = 0.0074) in myocardial tissue." (PMID 38782919, 2024).
influenza (2 papers, 2018 to 2025). An acute viral infection of the respiratory tract, occurring in isolated cases, in epidemics, or in pandemics; it is caused by serologically different strains of viruses (influenzaviruses) designated A, B, and C, has a 3-day incubation period, and usually lasts for 3 to 10 days. "DDX5 and DDX17 promote influenza, HIV-1 and Sindbis infection, and singularly have proviral or antiviral roles in other RNA or DNA virus infections." (PMID 40257982, 2025). "DDX5 and DDX17 both influence viral replication of human immunodeficiency virus (HIV), HBV and influenza." (PMID 40257982, 2025). "Notably, a specific cluster, indicated in pink, which is enriched in CORO1A-DEF6 network genes, demonstrated reduced activity following vaccination and correlated positively with DDX17 expression, and negatively with HAI titer and influenza-specific IFN-γ cytokine response." (PMID 30573748, 2018).
neuroblastoma (2 papers, 2024 to 2026). Neuroblastoma (NB) is the most common solid, extracranial childhood tumor. "Analysis of neuroblastoma tumours in which tracRNAs are abundant revealed that low expression of DDX17 and DDX5 genes is associated with high-risk tumours and poor overall patient survival, and inversely linked with MYCN oncogene amplification." (PMID 42209732, 2026). "Since the neuronal differentiation status is a critical factor in neuroblastoma development, DDX17 can be targeted for the regulation of differentiation in neuronal cancer therapy." (PMID 38689093, 2024). "DDX17 regulates the nuclear maturation of pri-miR-26a2 during the early stages of neuronal differentiation, and interestingly, processed mature miR-26a can reciprocally target DDX17 in neuroblastoma cells." (PMID 38689093, 2024). "Here, we demonstrate that the transcriptional readthrough induced by DDX17 depletion, either alone or in combination with DDX5, leads to an increased production of chimeric transcripts from tandemly oriented gene, or tracRNAs, in neuroblastoma cells." (PMID 42209732, 2026). "Collectively, our work reveals a novel function of MYCN in transcription termination and suggests that the deregulation of MYCN and DDX17/DDX5 expression in neuroblastoma may lead to the expression of non-canonical and potentially harmful RNA molecules." (PMID 42209732, 2026).
sarcoma (2 papers, 2017 to 2022). A usually aggressive malignant neoplasm of the soft tissue or bone. "Besides, the microprocessor contains several functional cofactors, including DEAD-box, RNA helicase, p72 (DDX17), and the Ewing’s sarcoma family of proteins, which together promote the fidelity and activity of DROSHA processing." (PMID 36139427, 2022).
uveal melanoma (2 papers, 2022 to 2025). A melanoma derived from melanocytes of the uveal tract. "Similarly, in uveal melanoma (UM), DDX17 expression was unfavorably associated with DNA damage, invasion potential, and DNA repair efficiency." (PMID 40526173, 2025). "A study on uveal melanoma found differential expression of DDX17 in clear-cell renal cell carcinoma (ccRCC) specimens suggests that DDX17 plays a key role in ccRCC metastasis." (PMID 35784274, 2022).
acute lymphoblastic leukemia (1 paper, 2025). Leukemia with an acute onset, characterized by the presence of lymphoblasts in the bone marrow and the peripheral blood. "Conversely, in acute lymphoblastic leukemia (ALL), a positive correlation was observed between DDX17 expression and quiescence." (PMID 40526173, 2025).
amyloidosis (1 paper, 2024). A disorder characterized by the localized or diffuse accumulation of amyloid protein in various anatomic sites. "Furthermore, DEAD Box Helicase 17, a similar protein to DDX24, has been implicated in amyloidosis, suggesting that the DEAD box helicase family might influence AD pathology." (PMID 38612434, 2024).
chronic kidney disease (1 paper, 2025). Impairment of the renal function secondary to chronic kidney damage persisting for three or more months. "Additionally, DDX17 also plays an important role in various diseases involves other organs or pathological processes, including neurodegenerative diseases, inflammation-related diseases, chronic kidney disease, metabolism-related diseases." (PMID 41322492, 2025).
colon adenocarcinoma (1 paper, 2023). "We found that DDX17 mRNA expression was increased in colon adenocarcinoma (COAD) tissues compared with normal tissues." (PMID 36593242, 2023).
Diabetes (1 paper, 2023). "In kidney tissue, the expression of DDX17 was also decreased in the Woroniecka Diabetes Glom database, which was in line with the DACH1 and TCF21 expression." (PMID 36875100, 2023).
endometrial cancer (1 paper, 2025). Primary or metastatic malignant neoplasm involving the endometrium (mucous membrane that lines the endometrial cavity). "Further analysis of DDX17 mutation sites and types showed that the mutation frequency was highest in endometrial cancer and the major mutations of DDX17 were missense mutations." (PMID 40526173, 2025). "Among the 32 cancer types analyzed, endometrial cancer had the highest frequency of DDX17 alterations, at 6.80%." (PMID 40526173, 2025).
fibrosis (1 paper, 2024). the formation of excess fibrous connective tissue in an organ or tissue in a reparative or reactive process. "Cardiac fibrosis levels and cell apoptosis rates of the Ddx17-cKO mice were also significantly higher than those of the control mice after Dox treatment." (PMID 38782919, 2024).
Glomerular sclerosis (1 paper, 2023). Accumulation of scar tissue within the glomerulus. "Mechanically, we speculated that the low expression of DDX17 might further down-regulate the activity of TCF21 and DACH1, worsen the glomerular sclerosis and renal interstitial fibrosis." (PMID 36875100, 2023).
Hantavirus infection (1 paper, 2025). "Prior studies report DDX17 translocation from nucleus to cytoplasm during Hantavirus infection—a strategy for evading host immune surveillance." (PMID 41402857, 2025).
herpesvirus infections (1 paper, 2025). "It is fascinating to speculate if DDX5 and DDX17 would play similar proviral roles in other herpesvirus infections." (PMID 40257982, 2025).
HIV-1 infection (1 paper, 2026). The type species of lentivirus and the etiologic agent of acquired immunodeficiency syndrome (AIDS). "For example, in HIV-1 infection, DDX17 promotes viral particle release by interacting with the Rev protein." (PMID 41367298, 2026). "The DQAD mutant of DDX17 impairs Gag processing, and DDX17 regulates Gag-Pol frameshifting to support HIV-1 infection." (PMID 41367298, 2026). "For instance, in HIV-1 infection, DDX17 promotes viral RNA packaging and stability through its core helicase domain interactions with viral proteins; in HBV infection, its C-terminal domain is involved in RNA termination regulation, restricting viral proliferation." (PMID 41367298, 2026).
immune deficiency (1 paper, 2023). "Given its critical role in innate immunity against virus invasion, the low DDX17 level in PBMC may aggravate immune deficiency in ESRD, and may result in chronic inflammation and increased oxidative stress to exacerbate kidney injury and loss of renal function." (PMID 36875100, 2023).
in situ breast cancer (1 paper, 2019). "Nevertheless, lower expression of both DDX5 and DDX17 has been reported in in situ breast cancer, along with increased MacroH2A1.1/MacroH2A1.2 ratios." (PMID 31164793, 2019).
melanoma (1 paper, 2013). A malignant, usually aggressive tumor composed of atypical, neoplastic melanocytes. "The upregulated expression of a few genes (DDX17, MARCH8, TNRC6A) was confirmed by RT-qPCR (using the limited residual RNA/cDNA of 2 of the microarrayed melanoma samples)." (PMID 24098529, 2013).
pancreatic cancer (1 paper, 2019). "A coexpression network revealed a hub comprising lncRNAs (MIR210HG, SNHG1, and LOC729970) and mRNAs (RAB3D, DDX17, and SPNS2) that presumably mediate drug resistance in pancreatic cancer." (PMID 31399552, 2019).
renal cell carcinoma (1 paper, 2016). "DDX17 (22q13.1), a nuclear endonuclease that produces 60 to 70 nucleotide pre-miRs, was identified as a metastasis-associated gene in renal cell carcinoma." (PMID 27453764, 2016).
retinoblastoma (1 paper, 2025). A malignant tumor that originates in the nuclear layer of the retina. "In retinoblastoma (RB), DDX17 was positively correlated with differentiation, angiogenesis, and inflammation, but negatively correlated with DNA repair, cell cycle, and DNA damage." (PMID 40526173, 2025).
sleep disorder (1 paper, 2025). A change from the patient's baseline sleeping pattern, in the hours slept and/or an alteration/dysfunction in the stages of sleep. "Identified by machine learning algorithms, DDX17 is one of the pivotal genes that is closely associated with sleep disorders, and is involved in a variety of cellular processes associated with RNA secondary structure alterations, and plays a core role in estrogen and testosterone signaling pathways." (PMID 41322492, 2025). "This helps to explain how DDX17 may influence sleep disorders." (PMID 41322492, 2025).
steatosis (1 paper, 2024). Increased lipid within the cytoplasm of cells. "Hepatic DDX17 protein levels were elevated in patients with NAFLD or NASH than in those with non‐steatosis." (PMID 38303609, 2024). "We found that DDX17 was substantially and positively correlated with steatosis (rho: 0.710, p < .001), lobular inflammation (rho: 0.515, p = .001), ballooning (rho: 0.625, p < .001) and fibrosis (rho: 0.418, p < .001), which are the major histological features of NASH." (PMID 38303609, 2024). "Furthermore, compared with the non‐steatosis group, the NAFLD and NASH group demonstrated substantially higher DDX17 expression in the quantification of IHC." (PMID 38303609, 2024).